DBP (D-box binding PAR bZIP transcription factor)
Description:
This transcriptional activator recognizes and binds to the sequence 5'-RTTAYGTAAY-3' found in the promoter of genes such as albumin, CYP2A4 and CYP2A5. It is not essential for circadian rhythm generation, but modulates important clock output genes. May be a direct target for regulation by the circadian pacemaker component clock. May affect circadian period and sleep regulation.
Synonyms: TaxREB302; DABP
Tractability: No criterion of Open Targets' tractability assessment is met for any kind of drug.
Gene: Protein-coding gene on chromosome 19 (48,630,030 to 48,637,379, reverse strand). Ensembl gene ENSG00000105516.
Subcellular location: Nucleus
Pathways (Reactome):
Circadian clock: Phosphorylated BMAL1:CLOCK (ARNTL:CLOCK) activates expression of core clock genes
Gene Ontology:
Molecular function: DNA-binding transcription activator activity, RNA polymerase II-specific; protein binding; protein heterodimerization activity; RNA polymerase II transcription regulatory region sequence-specific DNA binding; sequence-specific double-stranded DNA binding; DNA-binding transcription factor activity, RNA polymerase II-specific; RNA polymerase II cis-regulatory region sequence-specific DNA binding; DNA-binding transcription factor activity
Biological process: positive regulation of transcription by RNA polymerase II; regulation of transcription by RNA polymerase II; liver development; regulation of DNA-templated transcription
Cellular component: RNA polymerase II transcription regulator complex; chromatin; nucleus
Genetic constraint (gnomAD): Loss-of-function variants: 13 observed, 19.82 expected, observed/expected ratio (o/e) 0.66, 90% interval 0.43 to 1.04. The synonymous counts are far from expectation, so gnomAD's model fits this gene poorly and the ratio says little. Missense variants: 423 observed, 369.06 expected, observed/expected ratio (o/e) 1.15, 90% interval 1.06 to 1.24. Synonymous variants: 213 observed, 168.97 expected, observed/expected ratio (o/e) 1.26, 90% interval 1.13 to 1.41.
Homologues: Orthologues: pig DBP (96% identical), dog DBP (95% identical), mouse Dbp (93% identical), rat Dbp (92% identical), macaque DBP (88% identical), chimpanzee DBP (87% identical), guinea pig DBP (66% identical), tropical clawed frog dbp (51% identical), zebrafish dbpa (46% identical), zebrafish dbpb (46% identical), Drosophila melanogaster Pdp1 (35% identical), Drosophila melanogaster CG7786 (19% identical), and 2 more. Paralogues in human: HLF (41% identical), TEF (37% identical).
Diseases named in the same sentence as DBP in open-access papers:
DBP is named in the same sentence as 111 diseases in open-access papers, as found by Europe PMC text mining. Sharing a sentence is not in itself a finding about the gene and the disease. The quoted sentences say what the papers report.
vitamin D deficiency (19 papers, 2012 to 2025). A nutritional condition produced by a deficiency of VITAMIN D in the diet, insufficient production of vitamin D in the skin, inadequate absorption of vitamin D from the diet, or abnormal conversion of vitamin D to its bioactive metabolites. "This suggests a gene-environment interplay where DBP variants exacerbate vitamin D deficiency and ASD traits." (PMID 40362647, 2025). "Vitamin D deficiency is highly prevalent worldwide, and vitamin D-binding protein (DBP) a major regulator of serum vitamin D levels." (PMID 31830090, 2019). "Recently, large genome-wide association studies in European and two studies in Chinese reported another DBP polymorphism, rs2282679, had an association with vitamin D deficiency." (PMID 25890042, 2015). "Recently, two large genome-wide association studies in populations of European descent reported that rs2282679, another DBP polymorphism, had the strongest association with vitamin D deficiency." (PMID 25890042, 2015). "Moreover, only a SNP rs4588 of the DBP gene has been significantly associated (P = 0.04) with a clinical phenotype of multiple sclerosis and vitamin D deficiency." (PMID 41071764, 2025). "Because DBP gene polymorphisms have been linked to increased vulnerability to infections and vitamin D insufficiency in other populations, they may also have a role in COVID-19." (PMID 39139171, 2024). "In conclusion, increased severity levels in COVID-19 individuals may be explained by a genetic predisposition to vitamin D deficiency caused by distinct DBP polymorphisms." (PMID 35783611, 2022). "Taken together, data from the literature and the present results showing an association between the TT genotype of rs7041 and vitamin D deficiency support the hypothesis that this DBP gene variant is related to 25(OH)D concentrations." (PMID 28278285, 2017). "Still, it has been proposed that inherited gene polymorphisms in the genes related to the vitamin D-binding protein (DBP), vitamin D receptor (VDR), and vitamin D 1alpha-hydroxylase (CYP1alpha) are connected to the potential role of vitamin D deficiency in insulin resistance." (PMID 37764823, 2023). "In line with the role of DBP as responsible for generating a pool of circulating precursor, DBP null mice are much more prone to vitamin D deficiency when kept in conditions of vitamin D deficiency (no UVB light exposure and no vitamin D in their diet)." (PMID 31998239, 2019). "We were therefore interested to determine whether the strength of association between profound vitamin D deficiency and delayed sputum smear conversion differed according to genetic variation in VDR, DBP and CYP2R1." (PMID 26193879, 2015). "Neither do DBP-deficient mice develop rickets if they have access to sufficient vitamin D. Because the megalin receptor is a cargo receptor for a large number of proteins, loss of one of these membrane receptors can cause a variety of deficiencies, apart from vitamin D deficiency." (PMID 31998239, 2019). "In mice with targeted deletion of the Gc gene that completely lack DBP, PTH levels were not different between controls and animals without vitamin D toxicity or prolonged vitamin D deficiency (25OHD ≤6 ng/ml [15 nmol/l])." (PMID 25350643, 2014).
breast carcinoma (10 papers, 2007 to 2026). "Previous studies on vitamin D-associated SNPs and breast cancer risk have been focused mainly on genetic variants of the vitamin D receptor, and a few studies have been done on GC, which is the gene encoding DBP." (PMID 29291743, 2018). "It was hypothesized that women carrying the Gc2 allele(s) have a higher uptake of the DBP–25(OH)D complex or a better transport to the target organs, and different DBP glycosylation patterns in the Gc2 allele may explain the observed reduced breast cancer risk." (PMID 27143969, 2016). "Variants in CYP2R1, CYP24A1, CYP27B1, and DBP have been reported to influence circulating 25(OH)D concentrations and provide evidence for a hypothesis that these polymorphisms may be associated with breast cancer risk by altering vitamin D metabolism and signaling." (PMID 42292230, 2026). "For instance, in breast cancer, one of the predicted motif combinations contained both DBP and MAF." (PMID 28684851, 2017). "A nested case-control study within the Cancer Prevention study II (CPS-II) Nutrition Cohort examined the association between breast cancer and these four VDR SNPs (FokI, BsmI, ApaI, and TaqI), as well as SNPs in the 24-hydroxylase gene (CYP24A1) and vitamin D-binding protein gene (DBP)." (PMID 23533810, 2013). "In the breast cancer MDA-MB-468 cell line, Ad-E1A12 induced a high-level expression of the Ad5 E2A gene product DBP (DNA-binding protein) required for viral genome replication, although the yield of the viral genome and the expression of capsids were significantly impaired compared to Ad5." (PMID 27849011, 2016).
COVID-19 (9 papers, 2021 to 2024). A disease caused by infection with severe acute respiratory syndrome coronavirus 2. "Twenty-five articles have addressed the association between VDR and DBP genetic polymorphisms and treatment failure of VD in COVID-19." (PMID 37957515, 2024). "Genetic variants in the DBP gene, notably SNP in the rs7041 locus, were shown to be linked with the frequency of COVID-19 and death rates across nations in their study." (PMID 39139171, 2024). "In a commentary on our study, Speeckaert M and Delanghe J highlighted the potentially essential role of vitamin D binding protein (DBP) and its polymorphism on the link between low vitamin D levels and poor COVID-19 outcome." (PMID 36035432, 2022). "A study by Batur and Hekim (2019) evaluated the link between polymorphisms of the DBP-encoding gene GC at specific loci and COVID-19 positivity/death among several populations across 10 countries." (PMID 34835935, 2021). "Furthermore, our findings were supported by a study with 517 COVID-19 patients, which found that polymorphisms in the DBP gene were associated with illness severity (p = 0.005)." (PMID 35392098, 2022). "Furthermore, vitamin D-binding protein (DBP) has pleiotropic effects on the immune system that may influence inflammation associated with COVID-19." (PMID 36830936, 2023). "Furthermore, DBP, encoded by the GC gene, is known to have independent immunological and actin-scavenging effects that may affect inflammation in COVID-19." (PMID 36830936, 2023). "Meanwhile, DBP polymorphisms may be associated with COVID-19 prevalence and mortality." (PMID 35991038, 2022). "Further studies are needed to address the potential role of VDR activation and DBP in the pathophysiology of COVID-19 which take into account the genetic variations of vitamin D metabolic pathway." (PMID 36830936, 2023). "Further investigations are warranted to address the potential role of VDR activation and DBP in pathophysiology of COVID-19 considering the genetic variations of the vitamin D metabolic pathway." (PMID 36830936, 2023). "The Metabolism score encoded by the DBP and the CYP24A1 genes was associated with infection severity in a study of 517 Portuguese COVID-19 patients." (PMID 35783611, 2022). "A further in-depth examination of the positive association between the Metabolism score (DBP, CYP24A1) and the severity of COVID-19 revealed that the polymorphism DBP rs2282679 might explain the majority of the interesting correlation found." (PMID 35392098, 2022).
diabetes (9 papers, 2016 to 2024). "Recent studies have examined the connection between DBP polymorphisms and several autoimmune diseases, such as Graves’ disease, type 1 diabetes mellitus, systemic lupus erythematosus (SLE), and juvenile dermatomyositis (JDM)." (PMID 38892458, 2024). "A meta-analysis examined the association between two DBP gene polymorphisms (rs7041 and rs4588) and type 1 diabetes mellitus." (PMID 38892458, 2024). "Here, we sought to establish the role of DBP in α cell phenotype, function, and diabetes risk by combining studies in knockout mice with immunostaining analysis of pancreata from T1D donors and age-matched controls." (PMID 32553153, 2020). "In addition, there was a substantial difference in the allele frequency of the DBP HaeIII site between type 1 diabetes mellitus patients and healthy controls." (PMID 38892458, 2024). "This suggests that DBP has a function in the formation and maintenance of α-cell activity in diabetes." (PMID 38892458, 2024). "As such, DBP should be considered as an essential component of the α cell and the wider islet functional machinery with relevance for glucagon secretion during diabetes." (PMID 32553153, 2020). "The meta-analysis demonstrated that the DBP polymorphism was moderately associated with an increased susceptibility to type 2 diabetes mellitus in Asians, but no such association was found in European populations." (PMID 27143969, 2016). "Also, in Egyptians, there was no discernible correlation between DBP polymorphisms and type 1 diabetes mellitus." (PMID 38892458, 2024). "Thus, DBP regulates α cell phenotype, with implications for diabetes pathogenesis." (PMID 32553153, 2020).
Obesity (8 papers, 2017 to 2024). Accumulation of substantial excess body fat. "Certain DBP polymorphisms have been linked to obesity-related traits, such as higher BMI and body fat percentage." (PMID 38892458, 2024). "Customized dietary and supplement programs can be made easier with knowledge of how DBP polymorphisms affect the risk of obesity." (PMID 38892458, 2024). "A research study on the association between DBP SNPs and obesity revealed that certain DBP SNPs were significantly correlated with percentages of human fat mass." (PMID 37180138, 2023). "The circadian genes implicated in the stress-induced obesity are depicted as interacting in the following ways: CLOCK interacts with ARTNL and DBP." (PMID 39062927, 2024). "Similarly, expression of the circadian output gene DBP was markedly altered in obesity, while expression of the rhythmic integrator RevErbα exhibited only a modest change at one time point." (PMID 35600313, 2022). "CRY2 expression was related to age, DBP expression was related to age, tumor type, smoking history, and RORA expression was related to TNM stage, obesity index, and tumor type in KIRP patients (p < 0.05)." (PMID 34977153, 2021). "However, DBP, PER2, and NFIL3, and in turn many of the downstream genes they govern, all display marked dysregulation in obesity." (PMID 35600313, 2022). "In a time-course experiment with white adipose tissue biopsies from people with healthy weight or obesity or T2D, no variation in the rhythm and amplitude of core-clock (PER1, PER2, PER3, DBP, BMAL1, and CRY2), metabolic (PGC1), and clock-related (REVERB) genes could be observed in biopsy tissues." (PMID 37475884, 2023).
asthma (6 papers, 2011 to 2026). "Some DBP polymorphisms have been linked to increased production of pro-inflammatory cytokines and activation of macrophages, which can exacerbate the hyperreactivity and inflammation of the airways associated with asthma." (PMID 38892458, 2024). "The results presented here indicate that the two common SNPs in GC which determine DBP isoforms associate significantly with susceptibility to asthma, and that the Gc1 allele might confer a protective effect." (PMID 21810276, 2011). "In this study we set out to evaluate whether the variants of genes encoding for the key components of vitamin D pathway, including CYP2R1, VDR, and DBP, were associated with asthma or asthma-related phenotypes in a case-control design study in the Chinese Han population." (PMID 21810276, 2011). "Based on the close functional relationship between NFIL3 and DBP, it is safe to assume they may be significant candidate genes to devise options for treating patients with severe asthma." (PMID 37664635, 2023). "It should be pointed out that the roles of DBP and E2F8 in Th9 cells in the pathogenesis of other Th9-associated diseases such as allergy and asthma remain unknown and await further study." (PMID 36241625, 2022). "The polymorphisms rs7041 and rs4588 have an impact on the binding and transport efficiency of DBP, which in turn affects the bioavailability of vitamin D. This, in turn, may have an influence on inflammation and immunological responses, potentially playing a role in the development of asthma." (PMID 38892458, 2024).
viral infection (6 papers, 2013 to 2025). "Strikingly, when we visualized viral infection by staining with DBP or USP7 during infection with the ΔSS virus, we noticed a large fraction of cells possessed a novel VRC morphology characterized by exceptionally large, round or donut-shaped bodies." (PMID 36095031, 2022). "The detection of expression of DNA binding protein in BAdV-3 infected cell lysates by Western blot using anti-DBP serum confirm virus infection." (PMID 28082972, 2016). "We consider DBP a possible candidate because it forms homo-oligomers through its C terminus in a concentration-dependent manner, assembling RC-like structures even in the absence of a viral infection." (PMID 29997215, 2018).
metabolic syndrome (4 papers, 2017 to 2020). A cluster of metabolic risk factors for CARDIOVASCULAR DISEASES and TYPE 2 DIABETES MELLITUS. "In addition, the main finding of this study—that polymorphism rs7041 in the DBP gene is related to metabolic syndrome in PCOS and to lower 25(OH)D levels in the overall group—might signal a genetic link between metabolic disturbances in PCOS and low vitamin D levels." (PMID 28278285, 2017). "However, it is not known whether the DBP polymorphism affects the metabolic syndrome and its components through changes in vitamin D concentrations." (PMID 31007727, 2019).
periodontitis (4 papers, 2019 to 2024). An acute or chronic inflammatory process that affects the tissues that surround and support the teeth. "Collectively, these results indicate a critical role of DBP in orchestrating chronic periodontitis‐related behavioral abnormality, hippocampal synapse loss and neurogenesis deficits, in which the microglial activation may be indispensably involved." (PMID 39429161, 2024). "This study was conducted to explore the relationship between 1,25-dihydroxy vitamin D (1,25(OH)2D) and Vitamin-D binding protein (DBP) in patients with periodontitis and healthy controls." (PMID 31258606, 2019). "Finally, the vitamin D-binding protein (DBP) polymorphisms which are associated with bioavailable 25(OH)D are linked to the severity and progression of CKD and periodontitis." (PMID 38541146, 2024). "In addition to GCF, DBP has also been found in the periodontium apparatus, which is another medium that participates in the modulation of periodontitis." (PMID 31258606, 2019). "Rather, the DBP phenotype (affinity) should be taken into account, due to the likely implications in the clinical prognosis of CKD and periodontitis, as well as responses to vitamin D supplementation." (PMID 38541146, 2024). "Periodontitis in adults resulted in decreased levels of CSNK1D, RORA, CLOCK, DBP, NR1D1, ID2, and PER3 and a substantial increase in expression of FOS." (PMID 36472983, 2022).
adenovirus infection (3 papers, 2013 to 2024). "DBP could be used as a potential diagnostic target for human adenovirus infection given that the amino acid sequences of full length DBP are highly identical among the same species and the C-terminal domain is conserved among different species." (PMID 23516396, 2013). "These intermediate rings resembled the ring structures observed for DNA-binding protein (DBP) replication centers in adenovirus infection." (PMID 32584886, 2020). "Taken together, these finding suggest that DBP could function as an alternative antigen for the detection of HAdV antibodies and could serve as a novel antigen for early phase diagnosis of adenovirus infection." (PMID 23516396, 2013).
bipolar disorder (3 papers, 2009 to 2024). A disorder of the brain that causes unusual shifts in mood, energy, activity levels and the ability to carry out day-to-day tasks. "The study found that participants with bipolar disorder had significantly elevated levels of the vitamin D binding protein (DBP) compared to normal levels." (PMID 38920563, 2024). "RORB was initially chosen for investigation due to its altered expression level in DBP knock-out mice (an animal model of bipolar disorder) and due to the potential role of circadian clock genes in bipolar disorder." (PMID 19909500, 2009). "Also, knock-out of DBP in mouse resulted in bipolar disorder with both phases." (PMID 20856823, 2010). "We previously reported work establishing mice lacking the clock gene D-box binding protein (DBP) as a stress-reactive genetic animal model of bipolar disorder." (PMID 19909500, 2009).